IL6R (interleukin 6 receptor)
Diseases named in the same sentence as IL6R in open-access papers (continued):
Sharing a sentence is not in itself a finding about the gene and the disease.
asthma (68 papers, 2008 to 2026). "Consistent with our findings, a Mendelian randomization study investigating the relationship between IL6R signaling pathway blockade and respiratory disease risk demonstrated that IL6R inhibition is associated with reduced asthma risk." (PMID 41300562, 2025). "Higher IL6R levels were also associated with an increased risk of inflammatory conditions such as asthma and eczema (P = 2.04 × 10–4, Benjamini–Hochberg FDR = 2.60 × 10–4; P = 1.24 × 10–5, Benjamini–Hochberg FDR = 1.96 × 10–5, respectively)." (PMID 38565889, 2024). "Another study in Han Chinese population patients with asthma revealed that IL-6R rs12083537 G is associated with poor lung function." (PMID 39452786, 2024). "CCND1 and IL-6R have been reported to be associated with asthma inflammation and high serum IgE in patients." (PMID 38380329, 2024). "The link of the asthma susceptibility SNP in IL6R to sIL-6Rα levels prompted us to further investigate IL-6 trans-signaling." (PMID 38062491, 2023). "Phenome-wide association analysis confirmed that variants in the IL6R gene are associated with asthma and dermatitis." (PMID 35493452, 2022). "For example, the interleukin-6 receptor (IL-6R) is linked to increased risk of asthma and obesity, and its expression is positively associated with expression of TBC1D8 and negatively with expression of TBC1D16." (PMID 34301314, 2021). "The SNP Asp358Ala in the IL6R gene (A>C; rs2228145) is associated with various diseases, such as asthma, coronary heart disease, or type 1 diabetes." (PMID 32292581, 2020). "The SNP with rs4129267 is located at intron 8 (1q21.3) in the IL6R gene and has previously been reported to be associated with asthma susceptibility in Europeans." (PMID 32292581, 2020). "Sputum TNF-R2 and IL-6R were strongly associated with asthma exacerbations in both adults and children." (PMID 31395050, 2019). "A large Australian genome-wide association study identified a single-nucleotide polymorphism (SNP) located in the IL-6R gene (rs4129267) to be associated with asthma risk." (PMID 31395050, 2019). "In this modest number of genes identified several have been previously associated with airway biology and disease including e.g. TGFBR1, the receptor for TGFB1 involved in fibrosis and IL6R a cytokine receptor implicated in airway disease e.g. asthma." (PMID 31370853, 2019). "Interleukin-6 receptor (IL6R) has been reported to have important contributory effect in asthma treatment and have a potential role against pathogenic infection mastitis." (PMID 30326614, 2018). "Second, we sought to replicate the association between the IL-6R functional variant and an increased risk of asthma and allergy-related diseases using data collected from participants in the UK Biobank." (PMID 28334838, 2017). "Furthermore, a functional polymorphism in IL6R, for instance, has been demonstrated to raise the risk for AD and asthma while having a protective effect on RA." (PMID 36614274, 2023). "Other polymorphisms in the IL6R gene, such as rs4129267 (T allele), rs4845625 (C allele), or rs7529229 (C allele), were also reported to be associated with the risk of many diseases, such as asthma and CVDs." (PMID 35493452, 2022). "Genome-wide association studies (GWAS) have also reported that the single nucleotide polymorphism (SNP) rs2228145 (Asp358Ala)—a variant in IL6R that increases IL-6R shedding and promotes IL-6 trans-signaling—is associated with asthma prevalence, asthma severity, and lower pulmonary function." (PMID 33912579, 2021). "Additionally, genetic studies showed the associations of IL6R-related polymorphisms with asthma prevalence and severity, and lower pulmonary function." (PMID 33912579, 2021). "Despite the evidence on these associations which may suffer from unmeasured confounding, the causal role of sIL-6R in asthma (and hence the potential role of anti-IL-6R therapies) remains uncertain." (PMID 33912579, 2021).
asthma (continued). "Interestingly, a genome-wide association study identified a significant association between a single nucleotide polymorphism in the IL-6R gene and the risk of asthma in humans." (PMID 30442129, 2018). "The IL-6R coding SNP rs2228145 (Asp358Ala) is a potential modifier of lung function in subjects with asthma and may identify subjects at risk for more severe asthma." (PMID 28493984, 2017). "The Asp358Ala variant in the interleukin-6 receptor (IL-6R) gene has been implicated in asthma, autoimmune and cardiovascular disorders, but its role in other respiratory conditions such as chronic obstructive pulmonary disease (COPD) has not been investigated." (PMID 28334838, 2017). "Meta-analyses confirm significantly elevated serum IL-6 levels in asthma patients, correlating with disease severity, exacerbation frequency, and impaired lung function, while IL6R inhibition also demonstrates therapeutic benefits in T2DM patients." (PMID 41300562, 2025). "Our findings show that IL6R blockade significantly reduces the risk of COPD (OR = 0.71, 95% CI = 0.60–9.84) and asthma (OR = 0.82, 95% CI = 0.74–0.90), with protective trends for bronchitis, pulmonary embolism, and lung cancer." (PMID 38898459, 2024). "Our results showed that genetically proxied IL6R blockade was significantly related with a reduced risk of COPD (ORIVW = 0.71, 95% CI = 0.60–9.84) and asthma (ORIVW = 0.82, 95% CI = 0.74 − 0.90)." (PMID 38898459, 2024). "Our investigation focused on assessing the impact of these IL6R variants on the risk of multiple respiratory diseases, including COPD, bronchitis, asthma, pulmonary embolism, idiopathic pulmonary fibrosis, and lung cancer." (PMID 38898459, 2024). "The elevated genes include those associated with cellular proliferation (BRICD5), those previously associated with asthma and other inflammatory diseases (IL1RL1, IL6R) and those involved in inflammatory cell signaling (LIME1) and function (SLC11A1)." (PMID 37876037, 2023). "IL-6 interacts with IL-6Rα, and gp130 (a cytokine receptor) showed improved lung function in asthma patients with decreased plasma levels of IL-6Rα." (PMID 36187170, 2022). "In summary, our results revealed that the anti-IL6R (Sarilumab and satralizumab) are promising candidates for drug repositioning to asthma therapy." (PMID 35052792, 2022). "Recent study evaluated clinical and immunological responses to Tocilizumab, a humanized anti-IL-6R monoclonal antibody, in severe asthma." (PMID 35408882, 2022). "The meta‐analysis of the four studies resulted in a pooled RR for asthma with an increase in IL‐6R of 1.03 (1.01–1.04), certainty of evidence graded high." (PMID 36434743, 2022). "Recent mouse studies, along with the surprising GWAS results demonstrating a genetic link between IL-6R and human asthma, indicated that IL-6 (or IL-6R) is a priority for asthma treatment." (PMID 35052792, 2022). "Noteworthy, IL6R is considered a target for asthma drug repurposing based on its high target scores." (PMID 35052792, 2022). "Anti-IL-6R mAb that blocks both mIL-6R and sIL-6R involves activating IL-6 trans-signaling to prevent allergen-induced asthma exacerbations." (PMID 35052792, 2022). "This systematic review found casual effects of BMI, pubertal timing, linoleic acid, alcohol, MDD, immune related proteins ST2, IL1R, CASP‐8, IL6R and BTN3A2 on asthma risk." (PMID 36434743, 2022). "Among the seven promising target genes for asthma, we screened out IL6R as a highly promising target for treatment of asthma since the gene also acquired a high systemic score in functional annotations." (PMID 35052792, 2022).
asthma (continued). "Future studies are needed to investigate more detailed mechanisms whereby altered CEBPD expression and its posttranslational modifications affect IL-6R signaling in ASM to influence glucocorticoid responses in asthma." (PMID 35902923, 2022). "The gene expression of LHFP is correlated with IL6R, which plays an important role in asthma pathophysiology and obesity-related inflammation." (PMID 35906571, 2022). "Among these targets, we highly recommend drugs targeting IL6R for asthma repurposing, since the gene had a high systemic score in functional annotations." (PMID 35052792, 2022). "Experimental asthma models also demonstrated that IL-6R inhibitors attenuate the airway inflammatory response characterized by mixed granulocytic infiltration with elevated IL-6 and IL-6R levels." (PMID 33912579, 2021). "Using GeneAtlas data, our analysis finds 5 proteins—all interleukin receptors—whose levels causally contribute to asthma disease risk: IL1RL1, IL1RL2, IL2RA, IL4R, and IL6R." (PMID 32628676, 2020). "The IL-6R coding SNP rs2228145 (Asp358Ala), which increases IL-6R shedding and promotes IL-6 trans-signalling is associated with lower predicted FEV1 and is more frequent in the severe asthma clusters in the Severe Asthma Research Program (SARP) cohort." (PMID 31395050, 2019). "Our findings suggest that the role of the IL-6/IL-6R axis in asthma exacerbations warrants further investigation." (PMID 31395050, 2019). "Of the remaining eight genes, for five it can be argued that functional studies provided the first suggestion of a key role in asthma/allergies, namely IL6R,71CHIT1,72FCER1G,73IL18RAP74 and NDFIP175." (PMID 29333270, 2017). "Our data showed that GATA3, miR-125a-5p, FOXP3 and IL-6R are perturbed in the Treg cells of asthma patients." (PMID 26424054, 2015). "Such antibodies are already approved for the treatment of inflammatory diseases, and anti‐IL‐6R therapy may be effective in patients with severe, persistent, steroid‐resistant asthma." (PMID 41099307, 2026). "In addition, ERBB3, IL1R1, IL1RL2, IL6R, LRRC32, STAT6, and TNFRSF6B have been strongly linked to allergic diseases, such as asthma and rhinitis." (PMID 38773393, 2024). "By targeting IL6R, sarilumab and satralizumab could become novel candidate drugs for asthma treatment options." (PMID 35052792, 2022). "The role of IL6R in asthma has been supported by preclinical and clinical trial evidence." (PMID 35052792, 2022). "However, it will be helpful to carry out more studies from animal models and clinical trials to determine the mechanisms of anti-IL6R in asthma." (PMID 35052792, 2022). "Tocilizumab is a humanized IgG1 antibody targeting IL-6R – the receptor for IL-6, that is an interleukin recently attributed to contribute to asthma pathogenesis and which may represent a pathophysiological target." (PMID 36561741, 2022). "IL-6R rs4537545*T allele has been associated with increased circulating CRP levels, a decreased risk of RA in mixed ancestries, while an increased risk of diabetes and asthma from the UK Biobank Neale’s lab rapid GWAS (See Web Resources)." (PMID 33517400, 2021). "Furthermore, miR-125a-5p and IL-6R are perturbed in asthma patients, which provides basis for development of new therapeutic strategies against asthma." (PMID 26424054, 2015). "Finally, in an animal model of asthma CD4+CD25+ T cells isolated from anti-IL-6R antibody-treated mice exhibited marked immunosuppressive and antiinflammatory functions." (PMID 18315837, 2008). "Additionally, we found IL6R at chr1q21.3 (lead SNP: rs7529229) was shared between GlycA and asthma." (PMID 38704398, 2024). "IL-6 can also induce neutrophils to release soluble IL-6R which can act locally within the airway to activate eosinophils and act on airway epithelial cells to impair epithelial tight junction integrity and induce matrix metalloproteinases and the alarmin IL-33, contributing to pathology in asthma." (PMID 37180449, 2023).
asthma (continued). "In addition, the expression level of IL-6R was significantly downregulated in asthma patients." (PMID 26424054, 2015). "Among these proteins, MAPK3, IL6R, and CSF2—the most widely shared proteins—emerged as potential key regulators influencing the comorbidity of glucose metabolism dysregulation and asthma." (PMID 41300562, 2025). "PWAS identified IL6R, MAPK3, and CSF2 as the proteins most extensively shared between glycemic traits and asthma." (PMID 41300562, 2025). "IL6R had a total of 11 significant colocalisations, which included colocalisations with CAD as well as immunological conditions such as asthma." (PMID 38565889, 2024). "The complex IL-6/IL6R triggers a cascade that activates STAT3 and CEBP transcription factors, both involved in airway inflammation and asthma." (PMID 36979655, 2023). "In particular, seven gene targets (HMGCR, ADORA1, IL6R, CD86, BCR, PIK3CD, and NOS1) are prioritized for asthma drug repurposing." (PMID 35052792, 2022). "Higher levels of soluble IL-6R have been found in the sputum and broncho-alveolar lavage (BAL) fluid of people with asthma or COPD when compared to healthy controls." (PMID 33284859, 2020). "IL-6R, a prominent ADAM17 substrate linking the axis to STAT3 in trans-signaling, is a modifier of COPD as well as asthma." (PMID 29540993, 2018). "One asthma SNP (rs4129267) in the IL6R gene is in high linkage disequilibrium with a non-synonymous SNP (rs2228145), which maps to the cleavage site of IL-6Rα." (PMID 38062491, 2023). "Furthermore, our data reveals enhanced expression of IL6R and CRP in AECs derived from atopic-asthma patients." (PMID 37860000, 2023). "Whether the effect of IL6R on asthma arise from the modulatory role of IL6 on the immune response or a more direct effect of for example, sIL‐6R on CD4 T cells or airway epithelial cells is still unresolved." (PMID 36434743, 2022). "Lastly, it is possible that, despite support from human genetic association studies and experimental animal models of asthma, IL‐6R is not an appropriate drug target to prevent or treat allergen‐induced asthma exacerbations." (PMID 31223480, 2019). "Utilizing 26 genetic instruments for IL6R blockade, this study offers evidence suggesting that downregulation of IL6 signaling pathways may confer protective effect against the development of COPD and asthma." (PMID 38898459, 2024). "In addition to IL6R, we selected STAT3 for evaluation because IL-6/signal transducer and activator of transcription 3 (STAT3)-mediated signaling involved in various pathophysiological conditions including asthma and COPD." (PMID 38302925, 2024). "For instance, we identified novel pQTL SNPs explaining greater than 25% of variance in blood proteins such as interleukin 6 receptor, eotaxin-2, and E-selectin, which could be useful in studies of asthma and of non-pulmonary diseases." (PMID 27532455, 2016). "Prior links between these proteins and asthma or atopy exist (IL1RL1 and IL1RL2, IL2RA, IL4R, and IL6R), albeit not necessarily strong evidence for a causal link." (PMID 32628676, 2020). "Therefore, in this work we have compared the expression of CD26 and CD126 (IL-6Rα) in lymphocytes from different groups of donors: allergic (AA) and non-allergic (NAA) asthma, rhinitis, and healthy subjects." (PMID 31101830, 2019).
autoimmune disease (60 papers, 2010 to 2026). A disorder resulting from loss of function or tissue destruction of an organ or multiple organs, arising from humoral or cellular immune responses of the individual to their own tissue constituents. "Given the broad impact of IL-6 on immune cell function, several inhibitors have been developed to target the IL-6R signaling pathway as a treatment for autoimmune diseases and to control viral infection-associated inflammation." (PMID 40936905, 2025). "Currently, IL-6/IL-6R pathway inhibitors, such as tocilizumab, are predominantly utilised for their anti-inflammatory effects in autoimmune diseases, cytokine release syndrome, cancer-associated cachexia, and to enhance tolerance to immunotherapy." (PMID 39858048, 2025). "In our research, ten SNPs covering IL10 and IL6R genes were chosen based on previous association studies of autoimmune disorders, such as IBD, RA, MS and AS." (PMID 38822340, 2024). "Genetic variations in interleukin-10 (IL10) and interleukin-6 receptor protein (IL6R) genes are identified to be associated with autoimmune disorders." (PMID 38822340, 2024). "Due to its prominent proinflammatory function, IL-6 is regarded as a key player in the regulation of the immune response, and dysregulation of the IL-6/IL-6R system has already been associated with the pathogenesis of several autoimmune diseases." (PMID 37626843, 2023). "In conclusion, our study provides comprehensive evidence that variants in the IL6R gene are associated with the risk of inflammatory or autoimmune diseases and levels of inflammatory biomarkers." (PMID 35493452, 2022). "IL-6/IL-6R/gp130 signaling is implicated in the development of inflammatory and autoimmune diseases, including novel coronavirus disease 2019 (COVID-19)." (PMID 35493452, 2022). "Taken together, these results highlight IL-6R as a key regulator of Th17 cell metabolism via metabolic mediators that can be selectively targeted for the treatment of IL-6-associated pathologies such as autoimmune disease and infection-associated inflammation." (PMID 40936905, 2025). "Importantly, IL6 signaling through its receptor (IL6R) was associated with sex stratification as a risk factor for several autoimmune diseases." (PMID 39406500, 2024). "For men, 16 independent pleiotropic SNPs were detected, among which rs7512646 (PCPASSOC = 6.61 × 10–10) was novel, located in IL6R, a gene encoding a subunit of the interleukin 6 receptor complex and participating in the immune response and autoimmune diseases." (PMID 37644603, 2023). "However, IL-6 trans-signaling pathway (mediated by an interaction between IL-6/soluble IL-6R complex with gp130 subunit) has been implicated in the pathogenesis of malignant, inflammatory and autoimmune diseases." (PMID 33671821, 2021). "Therefore, it is speculated that rs2228145 impairs classical IL-6/IL-6R signaling and reduces the inflammatory response, thus leading to a lower risk of CVDs, inflammatory, or autoimmune diseases." (PMID 35493452, 2022). "Tocilizumab is an anti-IL-6R Ab developed for the treatment of autoimmune diseases, in particular rheumatological diseases." (PMID 39754984, 2025). "We showed that tocilizumab, an FDA-approved anti-IL-6Rα antibody for autoimmune diseases, inhibits tumour growth in both 2D and 3D HNSCC culture models." (PMID 39858048, 2025). "When IL-6 binds to mIL6R, the membrane-bound form of IL-6R, it forms a complex comprising IL-6, IL-6R, and gp130; this complex activates Janus kinases (JAKs), thus triggering two main signaling pathways involved in autoimmune diseases." (PMID 39201060, 2024). "Tocilizumab, a humanized IL-6R monoclonal antibody, has been used in autoimmune diseases closely related to humoral immunity." (PMID 37450932, 2024). "Dysregulated production of IL6 and IL6R has been suggested to contribute to the pathogenesis of many diseases, such as prostate cancer, multiple myeloma, and autoimmune diseases." (PMID 38140161, 2023).